IL6 (interleukin 6)
Diseases named in the same sentence as IL6 in open-access papers (continued):
Sharing a sentence is not in itself a finding about the gene and the disease.
tongue squamous cell carcinoma (4 papers, 2015 to 2020). A squamous cell carcinoma that arises from the tongue. "Importantly, IL6 was identified as one of the most promising predictors for early diagnosis and prognosis of tongue squamous cell carcinoma, the most common type of OSCC with high risk of local invasion and recurrence." (PMID 30847302, 2019). "The aim of this study was to investigate the serum levels of interleukin-6 in patients with oral tongue SCC." (PMID 26082902, 2015). "In one study, salivary levels of IL-1α, IL-6, IL-8, vascular endothelial growth factor A (VEGF-a) and TNF-α were able to predict the progression of tongue SCC from high-risk to neoplasm, serving as potential biomarkers for cancer screening and early detection." (PMID 26082902, 2015).
tonsillitis (4 papers, 2017 to 2021). Inflammation of the tonsillar tissue. "Levels of IL-1β, IL-2 and IL-6 showed a significant increase in the recurrent tonsillitis group when compared to the hypertrophy group." (PMID 30213594, 2020). "Although salivary levels of IL-6, IL-33 and TNF-α were significantly increased in patients with recurrent tonsillitis compared to healthy controls, these parameters were unable to differentiate between the diagnosis groups since significance was only achieved through single outliers." (PMID 34187480, 2021).
Toxocara infection (4 papers, 2015 to 2025). "Given the increased production of IL-6 both systemically and locally, this cytokine appears to be an interesting target for further research related to Toxocara infections." (PMID 40918106, 2025). "Likely, IL-6 controls their development, but still little is known about the role of these cells in toxocariasis." (PMID 26044883, 2015). "It seems unlikely that IL-6 plays the same role during Toxocara infection." (PMID 26044883, 2015). "We assessed the Th2-driving cytokine IL-6 and the early pro-inflammatory cytokine tumour necrosis factor (TNF) as these were previously shown to be affected upon Toxocara infection or Toxocara antigen stimulation." (PMID 33803269, 2021).
Trichiasis (4 papers, 2008 to 2019). Inversion and rubbing of the eyelashes against the globe of the eye. "Furthermore, we analyzed the effect of this photo treatment on the ensuing secretion of IL-6 and CCL2, two pro-inflammatory cytokines that have previously been identified as immunopathologic components associated with trichiasis in vivo." (PMID 22894815, 2012). "The upregulation of pro-inflammatory mediators and cell markers (CCL2, CCL3, CXCL5,IL1B, IL6, CHUK, FUT4 andPTPRC) is indicative of higher levels of inflammation and leukocyte infiltration in the conjunctival tissue of patients who developed ECA following trichiasis surgery." (PMID 37426632, 2019).
tuberculous pleurisy (4 papers, 1998 to 2019). "A recent study showed that EspC as an immunodiagnosis antigen also induced cytokine production of TNF-α, IL-6, and IFN-γ of pleural fluid mononuclear cells (PFMCs) from patients with tuberculous pleuritis (TBP)." (PMID 31134163, 2019). "IL-1β, IL-2, IL-6, TNF-α, PAI-1, and t-PA levels in pleural fluids of 40 patients with tuberculous pleurisy and 38 patients with tuberculous empyema were measured." (PMID 27034588, 2016).
Varicose veins (4 papers, 2022 to 2025). Enlarged and tortuous veins. "Increased IL-6 values at the level of varicose veins are a sensitive marker of local inflammation associated with elevated intravascular pressure in the affected district." (PMID 40362286, 2025). "Interleukin-6 is considered a surrogate endpoint of the varicose vein, but siravyadha is a treatment modality mentioned for siragranthi." (PMID 41404578, 2025). "Overall, the study supports sirāvyadha’s efficacy in reducing inflammatory biomarker IL-6 and subjective symptoms in varicose veins." (PMID 41404578, 2025). "IL-6 is considered to be a surrogate endpoint for varicose veins." (PMID 41404578, 2025). "Furthermore, numerous studies support the elevation of IL-6 levels in varicose veins." (PMID 41404578, 2025). "Some inflammatory and prothrombotic markers (e.g., IL-6, TNF-α, vWF, and PAI-1) has been reported to be significantly elevated in varicose veins." (PMID 35498031, 2022).
ventricular dilatation (4 papers, 2015 to 2023). "Newborns with hyperEPO only were not at significantly different risk of ventriculomegaly, whereas those with ISSI only (MPO, IL-1 β, IL-6, TNF- α, IL-8, MCP-1, VEGF, VEGF-R1, orange) were 2–5 times more likely to have ventriculomegaly than children without either hyperEPO or ISSI." (PMID 25793991, 2015).
Vertigo (4 papers, 2017 to 2025). An abnormal sensation of spinning while the body is actually stationary. "The results of this study reached a significant conclusion where higher IL-6 serum level post-COVID-19 infection led to a higher incidence of vertigo symptomatology, accounting for 10.8% of the variance (V+ status)." (PMID 36942191, 2023). "This is confirmed by recent findings highlighting the relationships between increased serum levels of IL6 and IL1 with vertigo, a specific complication of MD." (PMID 31906226, 2019). "Higher IL-6 serum levels post-COVID-19 infections lead to higher incidence rates of vertigo symptoms (p<.005), regardless of gender and age (p.005)." (PMID 36942191, 2023). "Studies have shown that the levels of IL-6 and TNF-α were significantly higher in patients with BPPV and vascular vertigo when compared to controls and patients with vertigo of nonvascular etiology." (PMID 36942191, 2023).
α-synucleinopathy (4 papers, 2015 to 2025). "Next, we analysed the association between log-transformed IL-6 and biomarkers for AD and synucleinopathy." (PMID 26434635, 2015). "To investigate how innate immune activation alters seeded α-synucleinopathy in wild type mice, we used an Interleukin (IL)-6 driven somatic transgenesis model." (PMID 28049533, 2017). "We also found that the changes in peripheral IL-6 levels were positively correlated to the changes in α-syn, which demonstrated that there could be mutual regulation between neuroinflammation and α-synucleinopathy in the development of POD." (PMID 32231560, 2020). "Moreover, studies of patients with PD, another neurodegenerative disorder characterised by synucleinopathy, display microglial activation, increased mRNA expression of IL-6 and elevated CSF levels of IL-6." (PMID 26434635, 2015). "Thus, contrary to our expectations that an inflammatory milieu might exacerbate α-synucleinopathy, we report that IL-6 induced immune preconditioning limits induction of α-synucleinopathy following injection of exogenous αSyn aggregates." (PMID 28049533, 2017). "Both IFN-γ and TNFα have been shown to be associated with neurodegeneration in PD mouse models while the role of other cytokines, such as IL-6 and IL-4 that are upregulated in PD patients, have not been studied before in mouse models of synucleinopathies." (PMID 28049533, 2017).
22q11.2 deletion syndrome (3 papers, 2021 to 2025). 22q11.2 deletion syndrome (DS) is a chromosomal anomaly which causes a congenital malformation disorder whose common features include cardiac defects, palatal anomalies, facial dysmorphism, developmental delay and immune deficiency. "Consequently, there is a growing body of evidence associating IL-6, a pro-inflammatory cytokine, with the neuroinflammatory process in 22q11.2 deletion syndrome." (PMID 38026692, 2023).
acanthosis nigricans (3 papers, 2021 to 2023). A melanotic cutaneous lesion that develops in the axilla and other body folds. "Despite showing a subtle effect on inflammation, our findings highlight the associations between acanthosis nigricans, adiposity, and IL-6." (PMID 36140983, 2022). "Mean IL-6 was higher in obese children with acanthosis nigricans (p = 0.048)." (PMID 36140983, 2022). "In our study, IL-6 was significantly higher in obese children with acanthosis nigricans." (PMID 36140983, 2022). "Importantly, mean IL-6 was significantly higher in obese children with acanthosis nigricans." (PMID 36140983, 2022). "Mean IL-6 was significantly higher in obese children with acanthosis nigricans than those without this condition (mean difference 0.547 pg/mL (p = 0.048))." (PMID 36140983, 2022).
acute disseminated encephalomyelitis (3 papers, 2020 to 2021). Acute disseminated encephalomyelitis (ADEM) is a demyelinating disorder of the central nervous system. "This study investigated the possible role of local immune changes and the activation state of the HMGB1/TLR4/Nf-κB/IL-6 pathway at the maternal–fetal interface during pregnancy in the pathogenesis of acute disseminated encephalomyelitis (ADEM)." (PMID 33597947, 2020). "Experiment has shown that CoVs play a destructive role in acute disseminated encephalomyelitis (ADEM) correlated with increased inflammatory mediators such as IL-6, IFN-γ, TNF-α, CXCL9, and CXCL10." (PMID 33708124, 2020). "We found increased levels of AQP4 in the placenta and fetal membrane in a patient with acute disseminated encephalomyelitis onset in pregnancy as compared to that in a healthy control; this may be due to the activation of the HMGB1/TLR4/Nf-kB/IL-6 pathway." (PMID 35069584, 2021).
AIDS dementia (3 papers, 2014 to 2020). "Expression levels of the molecules of interest, GSK-3β, β-catenin, NF-κB, and IL-6 from the Red/Green-HIV-1 infected human astrocyte data were overlaid with HIV encephalitis (HIVE) and HIV-associated dementia (HAD) disease and biological function using IPA pathway explorer." (PMID 33171974, 2020).
Alport syndrome (3 papers, 2012 to 2020). A rare renal disease characterized by glomerular nephropathy with hematuria progressing to end-stage renal disease (ESRD), frequently associated with sensorineural deafness, and occasionally with ocular anomalies. "STAT3 and IL6 were found to be increased in mice with Alport syndrome before anti-miR-21 treatment; the group, therefore, investigated the impact of STAT3 and IL6 inhibitors in Alport mice." (PMID 31044288, 2020). "Thus, inhibition of pro-inflammatory cytokine IL-6 has become a potential therapeutic strategy for Alport syndrome." (PMID 22937108, 2012).
anaplastic large cell lymphoma (3 papers, 2019 to 2025). Anaplastic large cell lymphoma (ALCL) is a rare and aggressive peripheral T-cell non-Hodgkin lymphoma, belonging to the group of CD30-positive lymphoproliferative disorders, which affects lymph nodes and extranodal sites. "In anaplastic large cell lymphoma (ALCL), JAK1 and STAT3 are activated by high levels of cytokines, including IL-6." (PMID 31861597, 2019).
androgenetic alopecia (3 papers, 2019 to 2023). "It is reported that Il6 mRNA and proteins are upregulated in balding DP cells in male-pattern baldness, and dihydrotestosterone-inducible Il6 inhibits the elongation of human hair shafts and promotes the regression of hair follicles in mice." (PMID 35457029, 2022). "These anti‐inflammatory activities might significantly affect the hair growth activity, as shown in previous studies that found increased levels of IL‐6, along with MCP‐3, IFNγ‐inducible protein‐10, and MIP‐1α, in balding zones of androgenetic alopecia compared with non‐balding zones." (PMID 37753679, 2023).
anisakiasis (3 papers, 2018 to 2025). Infection with roundworms of the genus anisakis. "IL6 and IL1β are pivotal cytokines in acute inflammation, and their overexpression aligns with clinical symptoms of anisakiasis, such as abdominal pain and systemic allergic reactions." (PMID 40552294, 2025). "While the dysregulation of IL-6 plays a crucial role in chronic helminthiasis, also potentially related to cancer, IL-6's role in anisakiasis is less clear." (PMID 39285481, 2024). "Whether Anisakis infection triggers pro- or anti-inflammatory IL6 responses remains to be elucidated." (PMID 30245697, 2018).
anthrax (3 papers, 2012 to 2015). "In pulmonary anthrax, the unlocking effect of cSN50 peptide on suppressed innate immunity mediators (TNFα, IL6, and MCP-1) is consistent with bimodal regulation of genome-wide response by this nuclear transport modifier." (PMID 22291977, 2012). "Elevated transcription of TNF-α, IL-1α, IL-1β, IL-4, IL-6, CCL5, CXCL2 and KC have been observed in both murine anthrax challenge models and in vitro macrophages and monocytic cell lines exposed to anthrax antigens." (PMID 26075052, 2015). "During anthrax infection, B. anthracis has been known to reach 107-108 organisms per milliliter of blood and induce high amount of cytokines such as TNF-α, IL-6, and IL-1β in primary macrophages and an experimental animal model." (PMID 25472474, 2014).
Apnea (3 papers, 2015 to 2023). Lack of breathing with no movement of the respiratory muscles and no exchange of air in the lungs. "Therefore, the increased levels of cytokines (i.e., IL-6 and TNF-alpha) that activate nuclear factor kappa B and the releasing of free fatty acids by excess adipose tissue might be involved in the pathogenic mechanisms leading to apnea in humans." (PMID 25760760, 2015). "Among the adipokines studied, leptin emerges as being most closely related to the severity of apnea, while the levels of IL-6, ET-1, and resistin are elevated during AMI regardless of OSA’s presence." (PMID 37834123, 2023).
asthenia (3 papers, 2007 to 2016). Clinical sign or symptom manifested as debility, or lack or loss of strength and energy. "Symptoms, primarily a consequence of elevated Interleukin-6(IL-6) production, are asthenia(65%), weight loss(67%) and fever(69%)." (PMID 17803812, 2007).
attention deficit-hyperactivity disorder (3 papers, 2020 to 2025). A disorder characterized by a marked pattern of inattention and/or hyperactivity-impulsivity that is inconsistent with developmental level and clearly interferes with functioning in at least two settings (e.g. at home and at school). "Nevertheless, both autism spectrum disorders (ASD) and attention deficit hyperactivity disorder (ADHD) are associated with increases in adaptive immune (T) cell cytokines, specifically Th2-like cytokines (IL-4, IL-6, and/or IL-10), or decreases in Th2-like cytokines (IL-2 and/or IFNγ)." (PMID 33424735, 2020). "In contrast, younger populations, such as children and adolescents, may show different cytokine profiles, with studies indicating elevated levels of IL-6 and IL-10 in children with attention-deficit/hyperactivity disorder (ADHD), which may overlap with depressive symptoms." (PMID 40305200, 2025).
avian influenza (3 papers, 2021 to 2025). Infection of domestic and wild fowl and other birds with influenza A virus. "Immune genes, such as interleukins IL6, IL12B, and IL25, located in the introgressed regions, play a crucial role in the immune response to most low pathogenic avian influenza strains." (PMID 39965774, 2025). "The therapy significantly damaged the blood’s oxidative capacity, altered histology, elevated the expression of the IL-6 and Nrf2 genes, fragmented DNA, and reduced the antibody titer against avian influenza and Newcastle disease." (PMID 39591046, 2024). "During the H5N1 avian influenza period, a sharply increase of circulating cytokines (e.g., IL-6, IL-2 and IFN-γ) could be a potential explanation for lymphocyte depletion in died patients." (PMID 34725309, 2021).
Barth syndrome (3 papers, 2012 to 2022). Barth syndrome (BTHS) is an inborn error of phospholipid metabolism characterized by dilated cardiomyopathy (DCM), skeletal myopathy, neutropenia, growth delay and organic aciduria. "Our results show that on average, Barth Syndrome patients possessed significantly higher IL-6:GF-1 ratios (p = 0.03) throughout the age groups analyzed compared to the healthy controls with mean." (PMID 22721508, 2012). "Thus two potential explanations for the higher IL-6 levels in Barth Syndrome include the lower levels of physical activity resulting from exercise intolerance and low grade inflammatory processes in Barth Syndrome." (PMID 22721508, 2012). "Higher levels of IL-6 and lower IGF-1 levels were observed in Barth syndrome patients compared with age-matched controls." (PMID 33001359, 2021). "Comparison of two anabolic growth mediators, IGF and GH, and two catabolic cytokines, IL-6 and TNF-α, in Barth Syndrome patients and healthy age-matched controls demonstrated a possible catabolic:anabolic imbalance in Barth Syndrome." (PMID 22721508, 2012).
basophilic leukemia (3 papers, 2017 to 2025). "Aucubin has been shown to inhibit TNF-alpha and IL-6 production in antigen-stimulated rat basophilic leukemia-2H3 mast cells." (PMID 28153003, 2017).
Benign Ovarian Tumors (3 papers, 2017 to 2023). "Significantly higher (p < 0.0001) levels of IL-6 were observed in PF of the OC patients than in the benign ovarian tumor group (n = 31)." (PMID 33062717, 2020). "The authors have suggested that determinations of IL-6 levels in PF can be useful in the differentiation between malignant and benign ovarian tumors." (PMID 33062717, 2020). "In addition, we determined the profile of IL-6 in both plasma and PF of patients with benign ovarian tumors and healthy donors." (PMID 33062717, 2020). "Moreover, the level of IL-6 in the PF of the OC patients was higher compared to the patients with benign ovarian tumors." (PMID 33062717, 2020).
blood pressure (3 papers, 2018 to 2024). "This suggests that suppression of elevated IL‐6 level by SYN is effective in reducing cardiac injury in HF‐HCD‐fed hyperglycaemic rats without any impact on the regulation of high blood pressure." (PMID 39264256, 2024).
bone sarcoma (3 papers, 2009 to 2021). A sarcoma that arises from the bone. "Moreover, elevated IL6 levels in peripheral blood of patients with bone sarcomas correlate with higher tumor extension and decreased overall survival." (PMID 26215971, 2015). "Besides IL6, other MSC-derived factor, such as IL-8, were reported to enhance the pro-tumorigenic properties of bone sarcoma cells." (PMID 34198693, 2021).
Borderline personality disorder (3 papers, 2022 to 2025). A personality disorder characterized by impulsive behavior and unpredictable, capricious mood. "In a study of a small sample of women hospitalized with borderline personality disorder, an association was found between dissociative symptoms and the increased expression of the interleukin-6 (IL6) gene." (PMID 35627228, 2022).
brainstem atrophy (3 papers, 2016 to 2019). "Only one patient had brainstem atrophy, whose interleukin-6 (IL-6) level in CSF was elevated (78.5 pg/mL)." (PMID 31612152, 2019).
bronchopneumonia (3 papers, 2022 to 2025). Acute inflammation of the walls of the terminal bronchioles that spreads into the peribronchial alveoli and alveolar ducts. "In bronchial pneumonia, the flavonoids group decreased the time to symptoms disappearance, the level of interleukin-6 (IL-6), interleukin-8 (IL-8), and tumor necrosis factor-α (TNF-α)." (PMID 35252093, 2022).
bulimia nervosa (3 papers, 2017 to 2025). A disorder characterized by recurrent episodes of binge-eating over which the individual feels a lack of control; these episodes of binge-eating are followed by recurrent compensatory behavior to prevent weight gain, usually self-induced vomiting. "Children in the top third of IL-6 also had lower odds of both bulimia nervosa (OR: 0.76, 95%CI: 0.34 to 1.67, p = 0.49) and binge eating disorder (OR: 0.76, 95%CI: 0.31 to 1.85, p = 0.54)." (PMID 32755646, 2020). "A positive correlation was found between leptin levels and bulimia nervosa (r = 0.42; p = 0.00), between leptin levels and binge eating (r = 0.38; p = 0.00), and between IL-6 concentrations and binge eating (r = 0.25; p = 0.04)." (PMID 30873471, 2017). "Results reveal elevations in interleukin (IL)-6 and IL-15 and reductions in IL-7 in people with anorexia nervosa in comparison to healthy controls, and no elevations in pro-inflammatory cytokines in people with bulimia nervosa." (PMID 41034374, 2025).